LYPLA2 (lysophospholipase 2)
Description:
Acts as an acyl-protein thioesterase hydrolyzing fatty acids from S-acylated cysteine residues in proteins such as trimeric G alpha proteins, GSDMD, GAP43, ZDHHC6 or HRAS. Deacylates GAP43. Mediates depalmitoylation of ZDHHC6. Has lysophospholipase activity. Hydrolyzes prostaglandin glycerol esters (PG-Gs) in the following order prostaglandin D2-glycerol ester (PGD2-G) > prostaglandin E2 glycerol ester (PGE2-G) > prostaglandin F2-alpha-glycerol ester (PGF2-alpha-G). Hydrolyzes 1-arachidonoylglycerol but not 2-arachidonoylglycerol or arachidonoylethanolamide.
Synonyms: APT-2; APT2; DJ886K2.4
Tractability: Small molecule: a structure with a bound ligand is known; a high-quality ligand is known. PROTAC: ubiquitination databases record sites on it; its protein half-life has been measured; a small molecule that binds it is known.
Target class: Enzyme; Hydrolase
Chemical probes: ML-211, ML349 (high quality), ML378
Gene: Protein-coding gene on chromosome 1 (23,791,110 to 23,795,544, forward strand). Ensembl gene ENSG00000011009.
Subcellular location: Cytoplasm
Subcellular location (Human Protein Atlas): Cytosol; Nucleoplasm
Pathways (Reactome):
Developmental Biology: L1CAM interactions
Gene Ontology:
Molecular function: cadherin binding; palmitoyl-(protein) hydrolase activity; phosphatidylcholine lysophospholipase activity; protein binding; hydrolase activity
Biological process: acylglycerol catabolic process; prostaglandin catabolic process; axon guidance; macromolecule depalmitoylation
Cellular component: cytoplasm; cytosol; extracellular exosome; Golgi stack
Genetic constraint (gnomAD): Loss-of-function variants: 7 observed, 29.43 expected, observed/expected ratio (o/e) 0.24, 90% interval 0.13 to 0.45. The upper end of that interval is the gene's LOEUF score, 0.45, which puts it in group 1 of 6, group 1 being the genes least tolerant of losing a copy. Missense variants: 206 observed, 312.24 expected, observed/expected ratio (o/e) 0.66, 90% interval 0.59 to 0.74. Synonymous variants: 112 observed, 119.47 expected, observed/expected ratio (o/e) 0.94, 90% interval 0.8 to 1.1.
Homologues: Orthologues: chimpanzee LYPLA2 (100% identical), dog LYPLA2 (100% identical), macaque LYPLA2 (100% identical), guinea pig LYPLA2 (99% identical), mouse Lypla2 (99% identical), pig LYPLA2 (99% identical), rabbit LYPLA2 (96% identical), rat Lypla2 (95% identical), zebrafish lypla2 (76% identical), tropical clawed frog lypla2 (73% identical), Caenorhabditis elegans ath-1 (46% identical). Paralogues in human: LYPLA1 (68% identical), LYPLAL1 (32% identical).
Diseases named in the same sentence as LYPLA2 in open-access papers:
LYPLA2 is named in the same sentence as 6 diseases in open-access papers, as found by Europe PMC text mining. Sharing a sentence is not in itself a finding about the gene and the disease. The quoted sentences say what the papers report.
neuroblastoma (1 paper, 2018). Neuroblastoma (NB) is the most common solid, extracranial childhood tumor. "Our data suggest that the cellular distribution of H- and N-ras regulated by LYPLA2 directly contributes to metastatic progression in our neuroblastoma model." (PMID 30228356, 2018).
phospholipidosis (1 paper, 2012). "Lysosomal phospholipase A2 (LYPLA2) has previously been linked with phospholipidosis, however, due to the lack of data in ChEMBL it was not present in the model." (PMID 22281160, 2012).
tumor (4 papers, 2023 to 2026). "LYPLA2 is the only depalmitoacylase that is associated with both tumor stage and prognosis of HCC." (PMID 38051779, 2023). "PLD and LYPLA2 genes presented up-regulated expression in tumor and lymphoid tissues (Fig. 4f7, f8, g7, g8)." (PMID 37164975, 2023). "GPC increased the stemness of OSCC tumor cells; ZIC2-regulated GPC metabolism through LYPLA2, inducing changes in the expression of the cancer stem cell markers Nanog and OCT4." (PMID 41856987, 2026).
LYPLA2 also shares sentences with these, for which no sentence is quoted: cancer (3 papers); lung carcinoma (1); oral squamous cell carcinoma (1).